TNF (tumor necrosis factor)
Diseases named in the same sentence as TNF in open-access papers (continued):
Sharing a sentence is not in itself a finding about the gene and the disease.
ovarian carcinoma (continued). "Another way in which this pro-inflammatory cytokine can orchestrate the TME in ovarian cancer was described by Charles and collaborators, who demonstrated that TNFα is able to bind to TNFR1 and maintain the production of IL-17 in CD4+ leukocytes." (PMID 33540543, 2021). "In ovarian cancer cell lines, C1q can induce apoptosis through the tumor necrosis factor (TNF) pathway." (PMID 33869223, 2021). "IL‐17 and TNF signaling pathway were identified to be related with chemotherapy sensitivity in ovarian cancer patients for the first time." (PMID 32441484, 2020). "Treatment with ICA-raw and ICA-Cubs can significantly increase the production of TNF-α within ovarian cancer cells, where the efficacy of the ICA-Cubs is significantly higher when compared with the ICA-raw treatment." (PMID 33374293, 2020). "DCs treated with IGF fail to mature and secret higher levels of IL-10 as well as TNF-α, which are suppressive immune factors in the ovarian cancer microenvironment." (PMID 33584699, 2020). "For example, in a mouse model of ovarian cancer, tumor cell-derived TNFα induced omental fibroblasts to produce TGFα, which in turn stimulated ovarian cancer EGFR and accelerated metastatic potential." (PMID 33069212, 2020). "The pro-inflammatory cytokines IL-6, IL-8 and TNF-α are commonly present in the ascites of ovarian cancer patients." (PMID 32727400, 2020). "In a subsequent cohort study, we will compare the survival rate of two groups of ovarian cancer patients (high TNFRSF6B expression and low TNFRSF6B expression), and the exact mechanism by which the TNF-α/TNFRSF6B signaling pathway inhibits ovarian cancer." (PMID 33083827, 2020). "For instance, in ovarian cancer, pDCs modulate neo-angiogenesis via TNF-α and IL-8 production upon CD40L activation." (PMID 32054102, 2020). "We have reported that SAA is preferentially localized to ovarian epithelial cells and the thecal-interstitial layers compared to granulosal cell layers in a mouse ovary, and ovarian carcinoma show tumor necrosis factor α (TNF)-induced SAA production." (PMID 30728901, 2019). "YAP has further been found to function downstream of the ovarian cancer-specific oncogene PRKCI (protein kinase C iota) to up-regulate TNF (tumor necrosis factor) expression, recruiting MDSC to inhibit cytotoxic T cell functions." (PMID 31052239, 2019). "Zhang and his coworkers have recently reported that goserelin induced apoptosis in epithelial ovarian cancer cells by partly upregulating factors of the TNF and TNF-receptor superfamilies." (PMID 31500399, 2019). "Previous work has demonstrated that the accumulation of pro-inflammatory cytokines, including tumor necrosis factor alpha (TNFα), within the tumor microenvironment enhanced migration, and invasiveness of breast and ovarian cancer cells." (PMID 31557960, 2019). "Cancer profiling array identified higher expression of TNF- α malignant ovarian tissue compared to normal ovarian tissue and also ovarian cancer cells compared to normal ovarian cells." (PMID 30581772, 2018). "Glypican-3 (GPC3) enhances M1 macrophage recruitment and increases the secretion of IL-12 and TNF-alpha in ascites of GPC3 expressing mouse models of ovarian cancer." (PMID 30274280, 2018). "APG-1387 induced RIP1- and TNFα-dependent apoptotic cell death in ovarian cancer through downregulation of IAPs proteins and induction of caspase-8/FADD/RIP1 complex, which drives caspase-8 activation." (PMID 29530056, 2018). "Even ovarian cancer cells appeared induction of proinflammatory chemokines in EGF- or TNF-responsive manner." (PMID 30034618, 2018). "Till date NF-κB’s role as a positive regulator for PIK3CA promoter in ovarian cancer cells by TNFα is known." (PMID 29169370, 2017). "To explore the relationship between Tregs, TNF, and IL-6 in ovarian cancer ascites, we created an in vitro system to study the effect of IL-6 and TNF within cell-free ovarian cancer ascites on TNFR2+ Treg and on TNFR2+ Teff frequency and function." (PMID 29163543, 2017).
ovarian carcinoma (continued). "The activation of CXCR4 results in the upregulation of the prometastatic cytokines IL-6, CXCL12, and TNFα in ovarian cancer cells and increases metastasis." (PMID 28275576, 2017). "Median concentrations of IL-10 and TNF-alpha in peritoneal fluid turned out to be the highest in ovarian cancer patients, followed by women with endometrioma and subjects with benign serous cysts." (PMID 28376925, 2017). "We observed that both the concentration of drug and the exposure time are important factors affecting TNF-α release by docetaxel in both breast and ovarian cancer cell lines." (PMID 28915246, 2017). "Collectively, our data emphasize that therapeutic intervention to platinum-resistant ovarian cancer cells favours a predominant quiescent state in SP via an interdependent positive feedback loop between TNFα-NF-κB and PI3K/AKT signalling." (PMID 29169370, 2017). "In ovarian cancer ascites, these mediators include IL-6, TNFα, as well as TLR and EGF receptor ligands." (PMID 28275576, 2017). "Median serum concentrations of TNF-alpha in ovarian cancer patients were significantly higher than in other study subjects." (PMID 28376925, 2017). "TNFα produced by TAMs also promotes invasion of ovarian cancer cells, the exact mechanism of which awaits further clarification." (PMID 28275576, 2017). "Ovarian cancer patients presented with significantly higher median serum concentrations of IL-10 and TNF-alpha than other study subjects." (PMID 28376925, 2017). "For example, Low-dose decitabine treatment recruit NK and CD8+ T cells, promotes their production of IFNγ and TNFα, and extends the survival of ovarian cancer." (PMID 27435207, 2016). "In TNF-α, mean value among ovarian cancer patients was increased (32.17±3.52 pg/ml) vs healthy controls (29.57±1.22 pg/ml)." (PMID 27902750, 2016). "Thirdly, flavonoids are shown to modulate the inflammatory cytokines such as TNF-α and IL-6, which is inseparable with ovarian cancer." (PMID 26960146, 2016). "To determine critical mediators in the signaling pathways associated with the TNF network, we established phosphoproteomic profiles using mass spectrometry analysis (LC-MS/MS) in a high TNF network expressing ovarian cancer cell line IGROV-1." (PMID 26871292, 2016). "The dependency of network genes on TNF was demonstrated by their down-regulation in tumour cells from patients with advanced ovarian cancer following the infusion of anti-TNF antibodies." (PMID 26871292, 2016). "In conclusion, C1q, via its globular domain, induced apoptosis in an ovarian cancer cell line SKOV3 via TNF-α induced apoptosis pathway involving upregulation of Bax and Fas." (PMID 28066412, 2016). "We investigated the effects of Caspase8 depletion onapoptosis and necroptosis of TNFα-stimulated ovarian cancer cell lines.Inhibition of NF-κB in ovarian cancer cells switched the effects ofTNFα signaling from proliferation to death." (PMID 28179987, 2015). "Release of multiple inflammatory cytokines into the plasma, including IFNγ, IL-1β, IL-6, IL-8, IL-10, TNFα, PlGF, and HSP90B1, is frequently associated with epithelial ovarian cancers (EOC)." (PMID 26858849, 2015). "In human breast and ovarian cancers, immune cells induced cancer cell invasion by TNF-α stimulation and increased expression of factors influencing invasion." (PMID 26317041, 2015). "ID8 ovarian carcinoma-conditioned BMDMs demonstrated a modest increase in TNFα and CCL2 following LPS stimulation, although this effect was not statistically significant." (PMID 26177198, 2015). "Deleting IKKβ in myeloid cells diminished expression of IL-10, IL-12p70, TNF-α cytokines and reduced size of tumors formed by ovarian cancer ID8 cells." (PMID 26427514, 2015). "Several studies have observed elevated TNF-α concentrations in the blood of ovarian cancer patients and patients with a wide variety of tumor types." (PMID 25624918, 2015).
ovarian carcinoma (continued). "Ovarian cancer patients express elevated serum TNFα,20 which can promote tumor cell death, or enhanceNF-κB signaling, depending on cellular context." (PMID 28179987, 2015). "The cytokine TNF-α is increased in malignant ovarian tumors compared with the normal ovarian surface epithelium." (PMID 25624918, 2015). "pDCs also contribute to angiogenesis by producing proangiogenic cytokines, such as IL-8 and tumor necrosis factor alpha (TNFα) in the ovarian carcinoma." (PMID 25254213, 2014). "Co-culture of macrophages with human ovarian cancer cell lines increases the invasiveness of tumor cells through TNFα-dependent activation of JNK and NFκB signaling pathways." (PMID 24936477, 2014). "Studies on colon and ovarian cancer have found that tumor-derived TNF-α plays an important role in tumor progression." (PMID 24676340, 2014). "Ovarian cancer cell lines and tumor biopsies have been shown to express elevated levels of IL-6, TNF, CXCL12, and its receptor CXCR4, and expression of these is co-regulated." (PMID 24936477, 2014). "We demonstrate that TNFα production is required to trigger necroptosis in the ovarian cancer cells, and that RIPK3 enhanced this process." (PMID 25356865, 2014). "Further, in TNFα-stimulated ovarian cancer cells this compound was equally toxic as IKKβ inhibition; however the IKKβ inhibitor clearly proceeded through a caspase-dependent mechanism while NSC676914A did not." (PMID 25324692, 2014). "TNFα appeared to be required for death, as a TNFα-neutralizing antibody was able to rescue cell survival in ovarian carcinomas expressing endogenous or ectopic RIPK3." (PMID 25356865, 2014). "Because of the link between TNF-α and TARS secretion by cultured ovarian cancer cells as well as the TNF-α association with myositis, we predicted that the serum levels for TARS would parallel those for TNF-α." (PMID 25163878, 2014). "In ovarian cancer, it has been shown that tumor-derived TNF-α plays an important role in promoting invasion and metastasis." (PMID 24676340, 2014). "Particularly, TNF has been shown to regulate chemokine networks in ovarian cancer cells through the nuclear factor-κB (NF-κB) signaling pathway." (PMID 24376747, 2013). "Further, cultured ovarian cancer cells expressed up to 1000 times more TNF-α mRNA than cultured normal ovarian surface epithelium." (PMID 23466883, 2013). "Ovarian cancer cells express high levels of tumor necrosis factor (TNF), indicating the potential importance of TNF as a regulator of the proinflammatory tumor microenvironment in this malignancy." (PMID 24376747, 2013). "Based on different responses to EGF or TNF in ovarian cancer cells, we compared those signaling components previously related with EGF- or TNF-activated Akt, Erk and IκB in ovarian cancer cells." (PMID 23800251, 2013). "In an ovarian cancer model, TNFα-mediated induction of IL-17-producing CD4+ cells led to the recruitment of myeloid cells into the tumor microenvironment and resulted in enhanced tumor growth." (PMID 24454480, 2013). "TNF-α has been reported to increase CD44 expression on ovarian cancer cells upon the activation of the c-Jun NH2-terminal kinase and, although not in the context of cancer, affects the glycosylation and sulfation of various glycoproteins." (PMID 23372803, 2013). "A significant positive correlation between the expression of genes involved in the TNFα signaling and those involved in Th17 pathways in patients with ovarian cancer was reported." (PMID 24454480, 2013). "Corilagin was reported to inhibit TNF-α secretion, but TNF-α was unable to be detected by regular ELISA from the culture supernatants of ovarian cancer cells." (PMID 23410205, 2013). "We used a PCR array for the chemokine network to examine the signature of chemokines and their receptors elicited by EGF and TNF in four ovarian cancer cell lines (OVCAR-3, SKOV-3, CaOV-3 and TOV-21G)." (PMID 23800251, 2013).
ovarian carcinoma (continued). "Our results indicate that CCL20, CXCL1-3 and CXCL8 are the primary chemokines induced by EGF or TNF and are elicited in these ovarian cancer cells via NF-κB, Akt and Erk signaling pathways." (PMID 23800251, 2013). "The present study explored the effect of TWEAK on macrophages, and the subsequent effects of TWEAK and macrophage-derived tumor necrosis factor-α (TNF-α) on ovarian cancer cell proliferation and metastasis." (PMID 23469193, 2013). "Since TNF is well known to be a proinflammatory cytokine abundantly expressed in ovarian cancer, we tested the effects of TNF on cell proliferation in SKA and SKCXCR2 cells." (PMID 24376747, 2013). "Results from phase I and phase II clinical trials using neutralizing antibodies against TNF-α in patients with ovarian cancer have demonstrated the positive therapeutic effects by blocking the Th17 action." (PMID 23227158, 2012). "We chose to use the IGROV1-Luc model of ovarian cancer, which has been reported to be TNF-α- dependent." (PMID 22792380, 2012). "In further support of the role of TNF in taxane cytotoxicity and resistance, we also report that both paclitaxel and docetaxel can induce TNF-α expression in A2780 ovarian carcinoma cells." (PMID 22225778, 2012). "In the course of the tumor microenvironment, TNF-α enhanced tumor growth via the inflammatory cytokine IL-17 in a mouse model of ovarian cancer and in patients with advanced cancer." (PMID 21943203, 2011). "Tumor-associated inflammatory cytokines such as IL-6 and tumor necrosis factor (TNF)-α probably regulate Th17 cells in the tumor microenvironment of ovarian cancer mouse model." (PMID 21943203, 2011). "Cytokines, such as TNF-α, IL-1, and IL-6, can also induce expression of ST6Gal-I, and interestingly, IL-1 and IL-6 have been shown to increase ovarian carcinoma cell motility and metastasis, as well as being able to up-regulate TNF-α production." (PMID 19014651, 2008). "The present result showed that COX-2 was induced by TNF-α in ovarian carcinoma cells and that TNF-α-induced COX-2 expression was suppressed by 15d-PGJ2, suggesting that COX-2 expression was under the control of PPARγ and NFκB pathway in the ovarian carcinoma." (PMID 15266333, 2004). "DEX can inhibit the surgical stress response and the release of stress mediators, promote the recovery of NK cell activity, and reduce the level of TNF-α, so it can be used as an effective immunomodulatory drug for patients with ovarian cancer during the perioperative period." (PMID 40309242, 2025). "Inflammatory cytokines in ovarian cancer cells, including tumor necrosis factor-α (TNF-α) and interleukin-1 (IL-1), promote malignant progression—such as tumor cell migration and invasion—by upregulating the expression of vascular cell adhesion molecule-1 (VCAM-1) and ICAM-1." (PMID 40140925, 2025). "In several animal models, TNF-α contributes to malignant progression, and there is evidence that TNF-α may have an autocrine or paracrine role in human ovarian cancer." (PMID 39795180, 2024). "Moreover, previous studies have reported a substantial upregulation of TNF-α mRNA in cultured ovarian cancer cells." (PMID 38384812, 2024). "Inflammatory cytokines like TNF, along with NF-κB signaling activation, may play a role in regulating biomarker expression in ovarian cancer." (PMID 39621651, 2024). "TNF-α has been shown to be involved in both endocrine and paracrine signaling in ovarian cancer." (PMID 39642218, 2024).
ovarian carcinoma (continued). "TNF-α can function as both an autocrine and paracrine growth factor in ovarian cancer." (PMID 37867861, 2023). "For example, we have detected 1-methylnicotinamide (p-value 8.03 × 10−7, but also detected by metabolomics analysis), functionally; MNA (methylnicotinamide) induces T-cells to secrete the tumor-promoting cytokine tumor necrosis factor alpha, being an immune regulatory metabolite in ovarian cancer." (PMID 37108611, 2023). "Furthermore, miR-199a-5p was also shown to target IkappaB kinase-beta in ovarian cancer cells, resulting in increased sensitivity to TNF-α-induced apoptosis following forced expression of miR-199a-5p." (PMID 37835506, 2023). "Notably, the PARP1 inhibitor talazoparib (BMN 673) elicited increased numbers of peritoneal CD8+ T cells and NK cells in an ovarian cancer mouse model and increased infiltration into ex vivo spheroids, in addition to increasing IFNγ and TNFα production levels." (PMID 37752135, 2023). "Importantly, the increase in CXCL1 expression by either EGF or TNF-α depends on the lineage of the ovarian cancer." (PMID 37108425, 2023). "Studies have shown that the TNF‐α level is abnormally high in patients with ovarian cancer." (PMID 37904699, 2023). "Endometriosis-related ovarian cancer might have a higher sensitivity to SMAC mimetics because those cancers have a greater tendency to express TNF-α compared with high-grade serous ovarian cancer." (PMID 36831656, 2023). "The results show that ovarian cancer in the high-risk group may be involved in epithelial-mesenchymal transition, KRAS signaling pathway, TNF NFKB signaling pathway, and angiogenesis, while the low-risk group is negatively associated with E2F and MYC pathways." (PMID 37859811, 2023). "The inverse correlation between the mRNA and protein levels of TNF-α and IL-6 has been reported in ovarian cancer cells by Israelsson and colleagues, which is possibly due to the complex regulatory mechanisms governing gene transcription, protein translation, and the stability of these cytokines." (PMID 38139181, 2023). "However, a retrospective analysis revealed that midazolam anesthesia was associated with less stable hemodynamics and an increased level of serum TNF-α than DEX anesthesia in patients undergoing radical resections of ovarian cancer." (PMID 36765695, 2023). "The levels of serum IL‐6, TNF‐α, and IFN‐γ are helpful to the clinical diagnosis of ovarian cancer recurrence, and the specificity of serum TNF‐α in predicting recurrence in ovarian cancer patients and the area under the ROC curve are higher than IL‐6 and IFN‐γ." (PMID 37904699, 2023). "Recent findings demonstrate that Cyst(e)inase treatment in combination with anti-PD-L1 checkpoint blockade synergistically enhanced T cell-mediated anti-tumor immunity, elevating tumoral lipid ROS and increasing populations of IFNγ/TNF expressing CD8 + /CD4 + T cells in an ovarian cancer model." (PMID 37170264, 2023). "Moreover, in ovarian cancer cells, ChoKα impairment overcomes Tumor Necrosis Factor (TNF)-Related Apoptosis-Inducing Ligand (TRAIL) resistance." (PMID 35250970, 2022). "D1 (A12) at 4.7 nM inhibits 50% TNF-α shedding and induces anti-ovarian cancer effects." (PMID 36466812, 2022). "One study reported that C1QB could upregulate the expression of Fas and TNF-α and induce apoptosis of ovarian cancer cells, either independently or through a caspase cascade reaction." (PMID 36313902, 2022). "In this context, pDCs have also been associated with poor prognosis in ovarian carcinoma patients by inducing IL-10-producing CD8+ Treg cells and inhibition of T cell proliferation, resulting in an induction of angiogenesis through production of TNF and IL-8, as reported in human ovarian cancer." (PMID 35406451, 2022). "The aim of this study was to investigate whether IL-6, IL-8, and TNF-α have sufficiently high sensitivity and specificity to be considered as new useful markers for diagnosis of ovarian cancer." (PMID 34573967, 2021).